RPL12 (ribosomal protein L12)
Description:
Component of the large ribosomal subunit. The ribosome is a large ribonucleoprotein complex responsible for the synthesis of proteins in the cell. Binds directly to 26S ribosomal RNA.
Synonyms: L12; uL11
Tractability: Small molecule: an approved drug acts on it; a structure with a bound ligand is known; a high-quality ligand is known. PROTAC: UniProt records ubiquitination sites on it; ubiquitination databases record sites on it; its protein half-life has been measured; a small molecule that binds it is known. Other modalities: a drug acting on it is in phase 2 or 3 trials.
Target class: Other cytosolic protein
Gene: Protein-coding gene on chromosome 9 (127,447,422 to 127,451,446, reverse strand). Ensembl gene ENSG00000197958.
Subcellular location: Cytoplasm
Subcellular location (Human Protein Atlas): Golgi apparatus; Vesicles
Pathways (Reactome):
Metabolism of proteins: Eukaryotic Translation Termination; Formation of a pool of free 40S subunits; GTP hydrolysis and joining of the 60S ribosomal subunit; L13a-mediated translational silencing of Ceruloplasmin expression; PELO:HBS1L and ABCE1 dissociate a ribosome on a non-stop mRNA; Peptide chain elongation; Ribosome Quality Control (RQC) complex extracts and degrades nascent peptide; SRP-dependent cotranslational protein targeting to membrane; ZNF598 and the Ribosome-associated Quality Trigger (RQT) complex dissociate a ribosome stalled on a no-go mRNA
Metabolism of RNA: Major pathway of rRNA processing in the nucleolus and cytosol; Nonsense Mediated Decay (NMD) enhanced by the Exon Junction Complex (EJC); Nonsense Mediated Decay (NMD) independent of the Exon Junction Complex (EJC)
Cellular responses to stimuli: Response of EIF2AK4 (GCN2) to amino acid deficiency
Developmental Biology: Regulation of expression of SLITs and ROBOs
Disease: Viral mRNA Translation
Metabolism: Selenocysteine synthesis
Gene Ontology:
Molecular function: protein binding; RNA binding; structural constituent of ribosome; large ribosomal subunit rRNA binding
Biological process: cytoplasmic translation; negative regulation of myoblast fusion; spermatogenesis; striated muscle contraction; translation
Cellular component: cytoplasm; cytosolic large ribosomal subunit; cytosolic ribosome; extracellular exosome; focal adhesion; membrane; postsynaptic density; cytosol; nucleolus; nucleus; ribosome; synapse
Genetic constraint (gnomAD): Loss-of-function variants: 10 observed, 20.88 expected, observed/expected ratio (o/e) 0.48, 90% interval 0.29 to 0.81. The upper end of that interval is the gene's LOEUF score, 0.81, which puts it in group 3 of 6, group 1 being the genes least tolerant of losing a copy. Missense variants: 134 observed, 184.92 expected, observed/expected ratio (o/e) 0.72, 90% interval 0.63 to 0.84. Synonymous variants: 73 observed, 68.84 expected, observed/expected ratio (o/e) 1.06, 90% interval 0.88 to 1.29.
Homologues: Orthologues: guinea pig Rpl12 (99% identical), macaque RPL12 (99% identical), mouse Rpl12 (99% identical), tropical clawed frog rpl12 (95% identical), zebrafish rpl12 (90% identical), Drosophila melanogaster RpL12 (79% identical), Caenorhabditis elegans rpl-12 (73% identical). Paralogues in human: MRPL11 (22% identical).
Diseases named in the same sentence as RPL12 in open-access papers:
RPL12 is named in the same sentence as 23 diseases in open-access papers, as found by Europe PMC text mining. Sharing a sentence is not in itself a finding about the gene and the disease. The quoted sentences say what the papers report.
hepatocellular carcinoma (2 papers, 2019 to 2020). A malignant tumor that arises from hepatocytes. "The mRNA level of RPS8, RPL12, RPL23A, RPL27, and RPL30 was detected as upregulated in hepatocellular carcinoma tissues and cell lines." (PMID 33584809, 2020).
Alzheimer disease (1 paper, 2024). A progressive, neurodegenerative disease characterized by loss of function and death of nerve cells in several areas of the brain leading to loss of cognitive function such as memory and language. "Conversely, the RPL12 and RPL15 genes exhibited significant up-regulation in brain capillary samples obtained from patients diagnosed with Alzheimer’s disease." (PMID 38540795, 2024).
Bardet-Biedl syndrome (1 paper, 2021). A ciliopathy with multisystem involvement. "For example, HES2, MAFB, RPS12, RPL12, RPS15, and AFF2 are all associated with cancer, whereas BBS12 is a gene related to Bardet-Biedl Syndrome, a multi-organ genetic disease that can involve hypoplasia of the uterus, ovaries, and fallopian tubes." (PMID 34215221, 2021).
endometriosis (1 paper, 2025). The growth of functional endometrial tissue in anatomic sites outside the uterine body. "NDUFS1 (OS) is thought to be associated with malignant transformation in endometriosis, whereas the role of RPL12 warrants more research." (PMID 40778374, 2025).
glioma (1 paper, 2023). A benign or malignant brain and spinal cord tumor that arises from glial cells (astrocytes, oligodendrocytes, ependymal cells). "In the intricate landscape of glioma pathogenesis, the elucidation of risk scores derived from pivotal hub genes—RPL3, RPL12, PTEN, IFNGR2, KLF10, PLAUR, MSN, and IKBIP—emerged as a critical component in understanding the disease’s progression and patient stratification." (PMID 38137116, 2023).
lupus (1 paper, 2014). "Autoantibodies to the 60S ribosomal protein L12, which is important in protein synthesis, has been detected in 3-28% of lupus patients." (PMID 24908187, 2014).
ovarian carcinoma (1 paper, 2024). A malignant neoplasm originating from the surface ovarian epithelium. "Notably, expression levels of RPS6, RPL12, CTNNB1, RPL7, RPS2, and CALM3 did not have any impact on the survival of ovarian cancer patients." (PMID 39309198, 2024).
Parkinson’s (1 paper, 2024). "Finally, although the EEF1A1, RPL12 and RPL15 genes have not been directly linked to ALS, they have been associated with other neurological diseases, such as Parkinson’s and Alzheimer’s." (PMID 38540795, 2024).
Sepsis (1 paper, 2025). Sepsis is defined as life-threatening organ dysfunction caused by a dysregulated host response to infection. "Thus, further investigation is warranted to determine whether Rpl12 is involved in ribophagy and PANoptosis of immune cells in sepsis." (PMID 40995563, 2025).
infection (6 papers, 2017 to 2025). The state of being infected such as from the introduction of a foreign agent such as serum, vaccine, antigenic substance or organism. "These proteins including the suspected allergen 60S ribosomal protein L12 detected at 48 and 72 hours post infection." (PMID 40665229, 2025). "Expression of RPS12 and RPL12 were upregulated after infection with A. veronii, which indicated more protein synthesis in cells." (PMID 37275236, 2023). "In addition, we validated the relative expression of some of the Rpl and Rps transcripts by RT-PCR and found the significantly lowered expression of Rpl4, Rpl12, Rps18, Rps19 during the infection compared to naïve animals." (PMID 35789215, 2022). "We found that the control (protein-producing)/NMD-sensitive transcript ratio was overall stable over time for both genes in non-infected cells, while it increased in favor of the control isoform (not targeted by NMD) at 3 and 9 h after infection for RPL12 and TMEM208, respectively." (PMID 36768954, 2023).
tumor (6 papers, 2011 to 2024). "Increased expression of various ribosomal proteins (rpS8, rpL12, rpL23a, rpL27, and rpL30) have been associated with tumor growth." (PMID 32973493, 2020). "Using qRT-PCR analyses further showed increased expression of Xpo1, Rpl12, Rps16, and Eif4a1 in RNA samples from primary prostate and lung metastatic tumor cells of TripleTg mice in comparison to those from PCa tissues of DoubleTg mice." (PMID 38336745, 2024). "A correlogram showed that RPL3, RPL12, and PTEN, whose coefficients of risk score were <0, had negative correlations with risk score, stromal score, immune score, and ESTIMATE score and positive relationships with tumor purity." (PMID 38137116, 2023). "Positive staining for XPO1, RPL12, RPS16, and pS6 proteins was also observed in both primary prostate and lung metastatic tumor cells developed in castrated TripleTg mice." (PMID 38336745, 2024). "Transcriptional profiles identified 39 genes that differentiated between 19 'metastatic' and 35 'non-metastatic' tumours, with molecular pathways involved in protein translation most strongly represented (MRPL33, RPL12, RPL27A, RPS5, RPS9)." (PMID 21385341, 2011).
neurological diseases (1 paper, 2024). "Additionally, while no studies directly related to ALS were discovered, other studies related to other neurological diseases were found in the cases of the EEF1A1, COX5A and RPL12 and RPL15 genes." (PMID 38540795, 2024).
RPL12 also shares sentences with these, for which no sentence is quoted: cancer (2 papers); B cell lymphoma (1); breast carcinoma (1); COVID-19 (1); Diabetes (1); genetic disease (1); lymphoma (1); osteosarcoma (1); prion disease (1); prostate carcinoma (1); serous ovarian cancer (1).